KRAS (KRas proto-oncogene, GTPase)
Diseases named in the same sentence as KRAS in open-access papers (continued):
Sharing a sentence is not in itself a finding about the gene and the disease.
tumor (continued). "The characterization of cellular profiles in the TME of CRC implies the immunomodulatory effect of KRAS mutation, particularly via promotion of inflammation and evasion of the immune response, ultimately leading to tumor progression, invasion, and progression." (PMID 35836817, 2022). "Apparently, the mutation sites and frequencies of KRAS gene were varied from diverse human tumor types." (PMID 35305624, 2022). "Kirsten Rat Sarcoma Viral Oncogene Homolog (KRAS) is the most frequently mutated oncogene, occurring in a variety of tumor types." (PMID 35922812, 2022). "In the larger-sample-size TCGA cohort, it also showed a higher mutation frequency of APC and PCBP1 in KRAS-Mut samples than in WT tumor samples (adjusted chi-square test, P < 0.05)." (PMID 35836817, 2022). "Compound ‘KD-8’ was discovered, which resulted in the inhibition of cellular and tumor growth of KRAS G12D mutated cells." (PMID 36531078, 2022). "These include CPP 24, 43 and 44 cell lines that have been freshly established from primary tumour samples that express mutated KRAS, and the CTC44 and 45 cell lines derived from circulating tumour cells (CTC)." (PMID 35740644, 2022). "Activating mutations in KRAS exon 2 can induce infinite proliferation of tumor cells, thereby freeing the pathway from the control of EGFR." (PMID 36465411, 2022). "Confocal fluorescence IHC study showed higher SOX9 staining in tumor compared to matched mucosa cryosections, especially in tumor harboring KRAS G12D and G12V mutations." (PMID 34919787, 2022). "The GAME score incorporates recalibrated tumor markers such as KRAS mutational status, extrahepatic disease presence, and Tumor Burden Score (TBS)." (PMID 35625968, 2022). "In summary, KRAS mutations independently, and in conjunction with other co-mutations influence tumour growth, changes in tumour microenvironment, and the efficacy of immunotherapy." (PMID 36284306, 2022). "Some studies integrated the relationship between the KRAS mutation and other oncogenic mutations, the PD-L1 expression, and/or the tumor mutational burden (TMB)." (PMID 35406400, 2022). "KRAS G12C mutation is the first mutation that has been targeted therapeutically, whereas KRAS G12D mutation seems to be an inhibitory factor for an effective immune response to the tumor." (PMID 35884381, 2022). "Co-occurring genetic alterations and the mutant KRAS allele copy number gains define a variety of tumor microenvironments, which lead similar histological tumors of different drug sensitivities." (PMID 36012655, 2022). "Meanwhile, KRAS mutation regulates tumor microenvironment via secreting molecules in a paracrine manner and inducing various chemokines, cytokines and growth factors, which contributes to the promotion and maintenance of malignancy." (PMID 36741696, 2022). "Subject characteristics, including age, sex, tumour location, degree of differentiation, KRAS gene mutation status, number of metastatic sites, metastatic sites and CA19-9, were independent predictors of PFS and OS." (PMID 34997351, 2022). "Regarding KRAS mutations in KRAS positive tumor DNA, G>T transversion in any of the KRAS hotspot positions (attributable to the main oxidative DNA damage, 8-oxo-dG) accounted for 30.0%." (PMID 35628513, 2022). "Gain- and loss-of-function experiments in pancreatic and colorectal cancer cell lines demonstrate that oncogenic KRAS promotes SG formation as an adaptive mechanism to a variety of tumor-associated stress stimuli." (PMID 35147163, 2022).
tumor (continued). "For example, it has been shown that NF2 (neurofibromatosis 2 or Merlin) serves as a tumor suppressor by inhibiting KRAS and that NF2 mutations can cause persistent Ras signaling." (PMID 36077838, 2022). "A recent study found that in NSCLC, KRAS mutations were closely associated with confirmed biomarkers of immunotherapy, including the tumor mutation burden, programmed death-ligand 1 (PD-L1) and tumor-infiltrating lymphocytes." (PMID 35517800, 2022). "In total, 2306 tumour samples were sequenced and actionable KRAS mutations were detected in 1084 samples (47%)." (PMID 35177674, 2022). "KRAS alterations were detected in 15% of all liquid biopsies, and in 19% of liquid biopsies with elevated tumor fraction, including mutations (95.5%), amplification (3.2%) and a combination of mutation with amplification (1.3%)." (PMID 36494601, 2022). "Analysis of a large cohort of NSCLC patients whose tumours harboured KRAS mutations revealed co-occurring KRAS mutations in up to 8% of tumours with the KRAS c.34G>T mutation." (PMID 35177674, 2022). "Recently, covalent inhibitors targeting specific KRAS-G12C mutation have been developed and shown satisfactory preclinical efficacy in KRAS-G12C mutated tumor models." (PMID 35281897, 2022). "Patient L2 TB and CDX presented a KRAS-mutant tumor with concurring mutations in genes KEAP1, STK11, and RBM10." (PMID 35511434, 2022). "Immunolabelling of cGAS and STING in metastatic CRC was performed and further complemented by histological classification, tumour grade, and KRAS, NRAS, and BRAF mutational status of mCRC." (PMID 36612217, 2022). "PDAC cells expressing oncogenic KRAS mutation exhibited high enhancements of basal macropinocytosis consuming extracellular proteins for rapid tumor proliferation, which is closely linked to autophagy." (PMID 36408139, 2022). "KRASG12V mutant/IGF2BP1 transgenic mice showed an increased tumor development linked to KRAS mRNA attachment to IGF2BP1." (PMID 36362424, 2022). "As a predictive marker, KRAS has been linked to round shape, nodules in non-tumour lobes, and multiple small nodules, as well as general radiomic profiles." (PMID 35406429, 2022). "Oncogenic RAS has been shown to be essential for tumor maintenance and KRAS mutation in CRC is associated with metastasis and poor prognosis." (PMID 34919787, 2022). "Mutations in the Kirsten rat sarcoma viral oncogene homolog (KRAS) oncogene have been considered as a driver of tumor initiation and maintenance." (PMID 36384590, 2022). "We tested the impact of KRAS hotspot variants by comparing gene expression profiles of each subset of tumor cells with a given KRAS mutation." (PMID 35995947, 2022). "We here developed a gold nanoparticle-based rapid strip test that has been applied for the first time for the multiplex detection of KRAS mutations in circulating tumor DNA (ctDNA) of CRC patients." (PMID 35200357, 2022). "Current clinical trials are stratifying patients only according to primary tumor site and KRAS G12C mutation." (PMID 35205778, 2022). "A previous study showed that neoantigen-specific T cell (HLA-C*08:02 restricted KRAS G12D) transfer resulted in tumor rejection, but yielded tumor evasion due to loss of MHC-I in one lesion." (PMID 35269735, 2022). "KRAS mutations present on tumor cells must be distinguished from KRAS mutations associated with clonal hematopoiesis on indeterminate potential (CHIP)." (PMID 35406400, 2022). "Investigating the role of tumor HLA status in the context of the clinical development of vaccines targeting KRAS mutations will play an important role in addressing biomarkers associated with clinical benefit from such therapies." (PMID 36494601, 2022). "We compared the clinicopathological characteristics, microsatellite instability status, BRAF classification, and tumor mutation burden of patients harboring the double mutants with those of patients harboring KRAS or BRAF single mutations." (PMID 35280113, 2022).
tumor (continued). "By preventing KRAS signaling, sotorasib inhibits both in vitro and in vivo cell growth as well as tumor growth, and it only causes apoptosis in KRAS (G12C) tumor cell lines." (PMID 36499382, 2022). "The identification of circulating tumor DNA (ctDNA) occurred later when certain gene alterations found in the tumor, such as KRAS mutations, were detected in the blood of patients." (PMID 35693015, 2022). "We reasoned that the signatures measuring RAS oncogenic activity in the lung cell line dataset would show enrichment of KRAS mutations in the high group given its role in tumour development in the lung." (PMID 36163168, 2022). "Altogether, these observations suggest that even if tumour clearance is pathologically confirmed, KRAS mutations persist despite clearing treatments." (PMID 35194118, 2022). "Of the 3,453 patients included in analysis, KRAS mutations were identified in 8.7% patients in overall; mutation rate and mutation subtypes varied widely across tumor systems and subtypes." (PMID 35359599, 2022). "These authors concluded that high levels of Fn were associated with poor prognoses, tumour growth, distant metastasis, poor differentiation, tumour-associated genes (KRAS mutation), and high microsatellite instability in CRC patients." (PMID 35454384, 2022). "We suggest that different KRAS mutations impart unique signaling properties that are preferentially capable of inducing tumor initiation in a distinct cell-specific manner." (PMID 36069770, 2022). "KRAS mutation was significantly associated with a shorter time in tumor recurrence compared with KRAS wild-type tumors." (PMID 35626213, 2022). "KRAS is one well-established tumor-driver gene associated with cancer initiation, development, and progression." (PMID 35563733, 2022). "Considering the close relationship between ARID1A and ARID1B, it would be compelling to investigate their tumor site-specific associations with KRAS pathway in future research." (PMID 36439454, 2022). "By contrast, KRAS mutation seems to be a good predictive factor for immune check-points inhibitors, reflecting a likely high tumor mutational board due to tobacco carcinogens, but some contradicting results are described in the literature." (PMID 35267628, 2022). "Tumor-derived EVs in these studies were enriched with biomarkers like glypican-1, a cell surface proteoglycan, along with harboring KRAS mutations." (PMID 35303879, 2022). "Cancer cells rewire their metabolic programs in response to changes in the tumor microenvironment and in oncogenic signals such as an activating KRAS mutation while AMG510 is a KRAS inhibitor targeting G12C-mutant KRAS." (PMID 36550998, 2022). "The results showed that 60% (252/422) of the tumor tissues had driver mutations, including 107 cases of KRAS (25%), 98 cases of EGFR (23%), 14 cases of ALK rearrangement (6%)." (PMID 35433677, 2022). "In the univariable analysis, only three factors were independent predictors of OS, synchronous CRLM tumours, KRAS mutated and postoperative chemotherapy." (PMID 35326950, 2022). "The analysis of patient data collected from Memorial Sloan Kettering (MSK) showed that patients with KRAS mutations had a worse prognosis after the surgical removal of the tumor." (PMID 36291766, 2022). "The model showed that high tumor heterogeneity was associated with a worst OS with an HR of 1.44, 95% C.I. 1.08–1.92, mostly in patients with KRAS mutated tumors." (PMID 36011003, 2022). "Intriguingly, our study discovered that KRAS mutational frequency was closely correlated with the tumor size, with larger tumors tending to enrich for KRAS mutations." (PMID 36439454, 2022).
tumor (continued). "Concurrent loss of LKB1 and KRAS mutations has shown enhanced metabolic activity and tumor disease burden reflecting a more aggressive biology than subjects with a single alteration in KRAS." (PMID 36661676, 2022). "Precedent RAS signatures likely contained genes associated with tumour progression, but our method based on the classification of KRAS wt as RAS-low samples worked at extracting RAS-specific genes from these signatures." (PMID 36163168, 2022). "We tested the possibility to assess residual tumour cells in resection and venous margins by the molecular presence of KRAS mutations." (PMID 35194118, 2022). "Activating mutations in KRAS are among the most prevalent oncogenic driver mutations in human cancers and are associated with tumorigenesis as well as aggressive tumor growth." (PMID 36494601, 2022). "The observed frequency of KRAS mutations in the late-stage sub-group is congruent with its status as a marker of aggressive tumor biology, portending poor clinical prognosis." (PMID 35448189, 2022). "This work highlights the context-dependency of KRAS-associated signaling and reinforces the importance of integrating the tumor microenvironment in the study of KRAS-associated effects." (PMID 35805073, 2022). "The prognosis of patients with KRAS-mutated tumors is associated with the level of PD-L1 expression in tumor cells." (PMID 35406400, 2022). "Since the direct identification of neoantigens from tumor tissues suggested that more potential neoantigens have yet to be identified, we screened cell lines with known oncogenic KRAS mutations and identified 2 more neoantigens that carry KRAS-G12V." (PMID 35982173, 2022). "Detection of mutant KRAS alleles was carried out on tumours (UFS) or tumour residues (NAT) and matched resection and venous margins." (PMID 35194118, 2022). "In tumor cells with mutations in KRAS or BRAF, mtHSP70 facilitates the interaction between PP1α and MEK1/2, which modulates MEK/ERK signaling activity, thereby promoting tumor cell proliferation." (PMID 35180892, 2022). "KRAS mutations can influence the presence of various immune cells in the inflammatory PDAC tumor microenvironment." (PMID 35883598, 2022). "A distribution of point mutations in KRAS also varies substantially in tumor tissues; for example in pancreas probability of the G12R mutation is 13% but it is only up to 2% in intestine." (PMID 36359850, 2022). "KRAS mutations also have a crucial role in autophagy stimulation to induce cell survival and tumor progression." (PMID 35883626, 2022). "On the other hand, some proteins encoded by lncRNAs have tumor-suppressive effects that inhibit the carcinogenesis of oncoproteins such as KRAS." (PMID 34489556, 2022). "We also discuss the relationship between KRAS mutations and the tumour microenvironment, and therapeutic strategies to target KRAS." (PMID 36284306, 2022). "Activation of PI3K/AKT signaling by mutant KRAS can cause ERβ degradation and disables its tumor suppressing effect." (PMID 36090030, 2022). "RAS oncogene mutations are found in about 50% of CRC tumours with KRAS being the dominant and NRAS less frequent, while BRAF mutations are reported in 5–10% of tumours, with up to 21% reported in cohorts of patients with unresectable metastatic CRC (mCRC)." (PMID 35610367, 2022). "In fact, the effectiveness of SHP inhibitors on KRAS G13D–mutated tumor cells has also been found in other studies." (PMID 35462913, 2022). "The dependence of KRAS-mutated NSCLC-tumour cells then led to decreased proliferation due to the lack of KRAS protein." (PMID 35220407, 2022). "On the tumour stage, KRAS mutation was reported highest in the late stage at 67.9% (95% CI: 59.3–75.5), while on location, the colon recorded the highest KRAS mutation of 61.2% (95% CI: 55.1–67.0)." (PMID 35782059, 2022). "Another study showed that KRAS mutations were correlated to an inflammatory tumor microenvironment and tumor immunogenicity, which benefitted the response to ICIs." (PMID 36741723, 2022).
tumor (continued). "The results of another study demonstrated that KRASIM, a highly conserved microprotein encoded by the putative lncRNA NCBP2-AS2, plays a tumor-suppressive role by interacting with KRAS in HCC cells." (PMID 34489556, 2022). "The blue line represents the KRAS-mutated tumours (mutKRAS) tumours and the grey dotted line represents the BRAF-mutated microsatellite stable (MSS) (mutBRAF/MSS) tumours." (PMID 34887523, 2022). "We hope to now expand that work by including two other NSCLC somatic tumor mutations (KRAS and KRAS G12C/V), and by overcoming several limitations of previous studies using more a precise exposure assessment and by limiting the exposure misclassification." (PMID 36078743, 2022). "These mutations render KRAS constitutively active, promoting tumor growth and evasion of immune destruction." (PMID 35565283, 2022). "It has become more evident that oncogenic KRAS mutations mediate the tumor microenvironment (TME), particularly by promoting inflammation and suppressing the immune response and ultimately leading to immune evasion and tumor progression 6-8." (PMID 35836817, 2022). "Expectedly, tumour tissues or remnants from patients who underwent NAT presented lower KRAS mutant allele frequencies (MAF) than patients eligible for UFS." (PMID 35194118, 2022). "Our study explores a unique class of tumor specific antigens, those in which a somatic mutation to cysteine is produced in an oncogenic driver, KRAS (G12C) which can be selectively targeted by a cell permeable irreversible inhibitor." (PMID 36099883, 2022). "In ascites fluid from a cohort of mixed KRAS-positive and wild-type tumours, KRAS mutations were detected in 100% of the KRAS-positive cohort, and in an additional 19% of tumours deemed wild-type by tissue biopsy." (PMID 35267615, 2022). "The lentiviral delivery of Cas9 and sgRNAs to cancer cells or tumor xenografts has allowed the selective inactivation of the mutated KRAS allele." (PMID 35326630, 2022). "Analysis of 900 CRCs with whole exome sequencing and epidemiologic annotations revealed an alkylating mutational signature that was associated with red meat consumption and distal tumor location, as well as predicted to target KRAS G12D/G13D." (PMID 36344948, 2022). "The term “genometastasis” is now used by some authors after some successful experiments on malignized normal cells with tumor-derived cfDNA, such as the transfer of the tumor specific KRAS mutation by adding the serum of a CRC patient to a healthy cell line." (PMID 35954375, 2022). "New studies focusing on intratumor heterogeneity should evaluate the correlation between the distribution across tumor cells of the KRAS G12C mutation and the response to its targeted inhibitors." (PMID 35205778, 2022). "Other authors showed that the presence of KRAS in the tumour tissue itself or in plasma was associated with a worse prognosis with a higher rate of recurrence and worse average survival." (PMID 35454771, 2022). "Several of these changes are anti-apoptotic in function such as PTEN−/−, Bcl-2 and Bcl-xL overexpression, while others such as the activating KRas mutation alter migration and in vivo tumor formation." (PMID 35406479, 2022).